ZC3H15 (zinc finger CCCH-type containing 15)
Description:
Protects DRG1 from proteolytic degradation. Stimulates DRG1 GTPase activity likely by increasing the affinity for the potassium ions.
Synonyms: DFRP1; LEREPO4; HT010; MSTP012
Tractability: PROTAC: ubiquitination databases record sites on it; its protein half-life has been measured.
Gene: Protein-coding gene on chromosome 2 (186,486,222 to 186,511,929, forward strand). Ensembl gene ENSG00000065548.
Subcellular location: Cytoplasm; Nucleus
Subcellular location (Human Protein Atlas): Cytosol
Pathways (Reactome):
Metabolism of proteins: Protein hydroxylation
Gene Ontology:
Molecular function: cadherin binding; protein binding; RNA binding; metal ion binding
Biological process: positive regulation of GTPase activity; cytoplasmic translation
Cellular component: cytoplasm; cytosol; nucleus
Genetic constraint (gnomAD): Loss-of-function variants: 9 observed, 41.44 expected, observed/expected ratio (o/e) 0.22, 90% interval 0.13 to 0.38. The upper end of that interval is the gene's LOEUF score, 0.38, which puts it in group 1 of 6, group 1 being the genes least tolerant of losing a copy. Missense variants: 353 observed, 456.45 expected, observed/expected ratio (o/e) 0.77, 90% interval 0.71 to 0.85. Synonymous variants: 138 observed, 151.02 expected, observed/expected ratio (o/e) 0.91, 90% interval 0.8 to 1.05.
Homologues: Orthologues: chimpanzee ZC3H15 (99% identical), dog ZC3H15 (99% identical), pig ZC3H15 (98% identical), rabbit ZC3H15 (98% identical), macaque ZC3H15 (97% identical), guinea pig ZC3H15 (97% identical), rat Zc3h15 (96% identical), mouse Zc3h15 (96% identical), rat AC115670.2 (88% identical), tropical clawed frog zc3h15 (79% identical), zebrafish zc3h15 (78% identical), Drosophila melanogaster CG8635 (53% identical), and 1 more.
Diseases named in the same sentence as ZC3H15 in open-access papers:
ZC3H15 is named in the same sentence as 21 diseases in open-access papers, as found by Europe PMC text mining. Sharing a sentence is not in itself a finding about the gene and the disease. The quoted sentences say what the papers report.
hepatocellular carcinoma (4 papers, 2016 to 2024). A malignant tumor that arises from hepatocytes. "Zinc finger CCCH type 15 (ZC3H15), a highly conserved protein implicated in different cellular processes associated with tumorigenesis, has emerged as a promising marker in hepatocellular carcinoma (HCC)." (PMID 39130630, 2024). "Recent studies indicated that ZC3H15 was involved in tumorigenesis and may be a potential biomarker in hepatocellular carcinoma (HCC) and acute myeloid leukemia (AML)." (PMID 35064102, 2022). "The aim of our study was to explore the clinical relevance and intrinsic functions of ZC3H15 in hepatocellular carcinoma (HCC)." (PMID 27191988, 2016). "Indeed, ZC3H15 acts as an important role involved in cell proliferation, apoptosis, cell adhesion, and transcription, and dysregulation of ZC3H15 has been reported in hepatocellular carcinoma (HCC) and acute myeloid leukemia (AML)." (PMID 35064102, 2022). "Zinc finger CCCH-type containing 15 (ZC3H15), a highly conserved protein involved in several cellular processes, which was responsible for tumorigenesis and may be a promising marker in myeloid leukemia (AML) and hepatocellular carcinoma (HCC)." (PMID 35027542, 2022).
gastric cancer (2 papers, 2022 to 2026). A primary or metastatic malignant neoplasm involving the stomach. "High ZC3H15 expression has also been reported in gastric cancer and is associated with poor prognosis." (PMID 41513632, 2026). "In DErrico and Cho’s dataset from the Oncomine database, we found that the expression of ZC3H15 mRNA was significantly increased from normal stomach tissues to gastric cancer tissues." (PMID 35064102, 2022). "Similarly, in gastric cancer, ZC3H15 downregulates FBXW7 transcription, leading to increased c-Myc stability." (PMID 41513632, 2026). "To confirm the role of ZC3H15 in GC, we analyzed the characteristics of GC patients related to ZC3H15 expression based on the TCGA database and the results indicated that ZC3H15 expression was significantly correlated with age, depth of invasion, and histologic grade of gastric cancer." (PMID 35064102, 2022). "The results demonstrated that silencing of ZC3H15 had no significant influence on the apoptosis in gastric cancer cells." (PMID 35064102, 2022). "However, the biological function and molecular mechanism of ZC3H15 in gastric cancer (GC) have not been studied." (PMID 35064102, 2022).
glioblastoma (2 papers, 2022 to 2026). The most malignant astrocytic tumor (WHO grade IV). "Recently, ZC3H15 has been shown to be highly expressed in glioblastoma (GBM) and is associated with poor prognosis." (PMID 41513632, 2026).
glioma (2 papers, 2022 to 2026). A benign or malignant brain and spinal cord tumor that arises from glial cells (astrocytes, oligodendrocytes, ependymal cells). "Interestingly, the GSEA analysis using the CGGA database indicated that high ZC3H15 expression was positively associated with EGFR signaling genes in glioma." (PMID 35027542, 2022). "ZC3H15 expression was dramatically associated with grade and TCGA subtypes in glioma." (PMID 35027542, 2022). "Furthermore, the clinical data from the TCGA database also indicated that gene copy number gain for ZC3H15 was linked to high expression of ZC3H15 in glioma." (PMID 35027542, 2022). "To further determine the role of ZC3H15 in glioma, we analyzed the characteristics of glioma patients related to ZC3H15 expression based on the CGGA database." (PMID 35027542, 2022). "We also analyzed the data obtained from the TCGA database, the expression of ZC3H15 is the highest in GBM which is the top level of glioma." (PMID 35027542, 2022). "We downloaded the data from the CGGA database and ranked them by the WHO analysis method, the expression level of ZC3H15 increased with the malignant degree of glioma." (PMID 35027542, 2022). "In gliomas, ZC3H15 suppresses CBL expression, thereby enhancing EGFR protein stability." (PMID 41513632, 2026).
Hepatitis (2 papers, 2016 to 2023). Inflammation of the liver. "Furthermore, adoptive transfer of Zc3h15-expressing macrophages in RIPK3M-KO mice augmented IR-triggered liver inflammation and cell death." (PMID 37841640, 2023). "Other clinical characteristics, including age, gender, tumor size, distant metastasis, encapsulation, UICC stage, and hepatitis background were not directly related to the expression of ZC3H15." (PMID 27191988, 2016).
attention deficit-hyperactivity disorder (1 paper, 2024). A disorder characterized by a marked pattern of inattention and/or hyperactivity-impulsivity that is inconsistent with developmental level and clearly interferes with functioning in at least two settings (e.g. at home and at school). "For example, male-specific pQTL rs3213946 is also eQTL for several genes (ITGAV, FAM171B, ATP6V1B2 and ZC3H15) and associated with diseases such as inflammatory bowel disease, coronary artery disease, and attention deficit hyperactivity disorder." (PMID 38326779, 2024).
bone cancer (1 paper, 2026). A primary or metastatic malignant neoplasm affecting the bone or articular cartilage. "In the bone cancer pain model, ZC3H15 exacerbates neuronal oxidative stress through the KEAP1/NRF2 pathway and activates microglial inflammatory response through IκB α/NF - κ B activation." (PMID 41513632, 2026).
endometriosis (1 paper, 2011). The growth of functional endometrial tissue in anatomic sites outside the uterine body. "The expression of ZC3H15, taken as an example (gene number 16), typifies the heterogeneity of single gene expression among the 10 endometriosis specimens." (PMID 22203846, 2011). "Thus, among the endometriosis patients, ZC3H15 has a heterogeneous expression: while it is unchanged in 4 specimens (GSM175766, GSM175774, GSM175768, and GSM175773), it is overexpressed in GSM175769 and underexpressed in 5 specimens (GSM175767, GSM175770, GSM175772, GSM175771, and GSM175775)." (PMID 22203846, 2011).
lentivirus infection (1 paper, 2016). Virus diseases caused by the Lentivirus genus. "ZC3H15 mRNA and protein levels were reduced in SMMC7721 cells through lentivirus infection." (PMID 27191988, 2016).
lung adenocarcinoma (1 paper, 2026). A carcinoma that arises from the lung and is characterized by the presence of malignant glandular epithelial cells. "It is worth noting that TCGA database analysis shows that ZC3H15 mRNA is significantly overexpressed in various malignant tumors, including lung adenocarcinoma." (PMID 41513632, 2026). "Furthermore, ZC3H15 was found to be highly expressed in A549/DDP cells, a human lung adenocarcinoma cisplatin-resistant cell strain." (PMID 41513632, 2026).
lung carcinoma (1 paper, 2026). "Subsequently, we sought to determine the biological function of ZC3H15 in NSCLC using lung cancer cell lines." (PMID 41513632, 2026). "Immunofluorescence experiments revealed that ZC3H15 was mainly localized in the cytoplasm of lung cancer cells." (PMID 41513632, 2026). "Next, we used western blot analysis to examine ZC3H15 expression levels in eight lung cancer tissues and normal tissues." (PMID 41513632, 2026). "Together, our findings suggest that ZC3H15 promotes the proliferation, migration and invasion of lung cancer cells through activation of the AKT-mTOR signaling pathway." (PMID 41513632, 2026). "Together, these results confirm that ZC3H15 plays an important role in promoting the proliferation, migration and invasion of lung cancer cells." (PMID 41513632, 2026). "ZC3H15 protein expression levels were found to be higher in lung cancer tissue than the corresponding adjacent tissue [P < 0.01] and normal tissue." (PMID 41513632, 2026). "Our analysis of 1149 TCGA and matched samples showed that ZC3H15 mRNA levels were significantly increased in lung cancer tissues [P < 0.001]." (PMID 41513632, 2026). "Our findings demonstrate that ZC3H15 promotes lung cancer progression through activation of the AKT-mTOR pathway in these cells, suggesting a potential functional interaction with oncogenic KRAS signaling." (PMID 41513632, 2026). "In addition, overexpression of ZC3H15 increased the migration and invasion abilities of lung cancer cells." (PMID 41513632, 2026). "Furthermore, high expression of ZC3H15 was found to be a predictor of poor prognosis in lung cancer patients [P = 0.003]." (PMID 41513632, 2026). "Although we have demonstrated the role of ZC3H15 in promoting tumor proliferation and migration by regulating the AKT signaling pathway in lung cancer." (PMID 41513632, 2026). "Nevertheless, the findings of this study further deepen our understanding of the biological function of ZC3H15 in lung cancer and suggest that it promotes malignant progression of non-small cell lung cancer by regulating PTEN protein stability." (PMID 41513632, 2026).
lymph node metastasis (1 paper, 2026). "Based on the potential correlation between ZC3H15 and tumor growth and lymph node metastasis, as well as its association with the cell cycle identified by gene set enrichment analysis (GSEA), we hypothesized that ZC3H15 may play an important role in cell proliferation, migration and invasion." (PMID 41513632, 2026).
malignant glioma (1 paper, 2022). A grade III or grade IV glioma arising from the central nervous system. "Moreover, IHC staining assays revealed that ZC3H15 expression in malignant gliomas was significantly higher than the adjacent/normal brain tissue, and increases along with malignant stages." (PMID 35027542, 2022).
cancer (8 papers, 2016 to 2026). A tumor composed of atypical neoplastic, often pleomorphic cells that invade other tissues. "This study reveals the important role of ZC3H15 in NSCLC, and shows that high ZC3H15 expression levels are closely associated with malignant tumor progression and poor prognosis." (PMID 41513632, 2026). "This study integrated transcriptome data between cancer and adjacent tissues from GEO and TCGA databases through bioinformatics analysis, and screened zinc finger CCCH-type containing 15 (ZC3H15) as a key differentially expressed gene in NSCLC." (PMID 41513632, 2026). "Consistantly to our results, lower level of ZC3H15 correlates with a better survival outcome of cancer patients." (PMID 40696438, 2025). "Literatures have documented that ZC3H15 plays a pivotal role in facilitating the progression of multiple cancer types by safeguarding the stability of c-Myc and EGFR proteins." (PMID 40696438, 2025). "In this study, we illustrated the role of ZC3H15 that stabilized c-Myc protein level via inhibiting FBXW7 transcription to promote cancer progression." (PMID 35064102, 2022). "In conclusion, we illustrated the role of ZC3H15 as a transcription factor that stabilized the EGFR protein level via inhibiting CBL transcription to promote cancer progression." (PMID 35027542, 2022). "To determine its value as a new cancer biomarker that would assist in the follow-up management after surgery, we examined and characterized ZC3H15 as an independent prognostic factor of outcomes of HCC patients." (PMID 27191988, 2016). "Future studies could be extended to other tumor types to explore the role of ZC3H15 in tumor heterogeneity and metastasis, as well as its potential as a pan-cancer marker." (PMID 41513632, 2026). "Current research on ZC3H15 in cancer has primarily explored its role in transcriptional regulation." (PMID 41513632, 2026). "Moreover, exploring the potential therapeutic strategy targeting ZC3H15 for treating diseases related to telomerase dysfunction, such as cancer and aging-related disorders, is imperative." (PMID 40696438, 2025). "Overexpression of ZC3H15 was found in 8 of 20 cancer types through Oncomine data-mining analysis." (PMID 35064102, 2022). "This suggests ZC3H15 profoundly effects cancer cell proliferation and survival in HCC." (PMID 27191988, 2016). "ZC3H15 may represent a new target for cancer treatment and anti-aging therapies." (PMID 40696438, 2025).
tumor (5 papers, 2016 to 2026). "Based on this, we plan to systematically explore the regulatory role of ZC3H15 on the AKT-mTOR pathway in different tumor types, as well as the tissue-specific differences and molecular basis of this regulatory mechanism in subsequent studies." (PMID 41513632, 2026). "We found that overexpression of ZC3H15 promoted tumor growth and cisplatin resistance in vivo, which was dependent on the DFRP structural domain of ZC3H15." (PMID 41513632, 2026). "The results showed that ZC3H15 downregulation significantly retarded the tumor formation capabilities of GBM cells." (PMID 35027542, 2022). "To investigate the role of ZC3H15 in the tumor growth of GC cells, we performed the subcutaneous xenograft experiment and then found that ZC3H15 knockdown significantly retarded the tumor growth of GC cells." (PMID 35064102, 2022). "Taken together, ZC3H15 was an oncogene acting in tumor cells and with its great functional ability to control numerous cellular progressions." (PMID 35027542, 2022). "According to ZC3H15 IRS scores, patients were divided into four groups and in most tissues ZC3H15 was highly expressed in tumor and low in peritumoral counterpart tissues." (PMID 27191988, 2016). "ZC3H15 protein and mRNA levels were approximately 2 to 3 times higher in tumors than in matched non-tumor tissues." (PMID 27191988, 2016). "ZC3H15 predominantly presented in the cytoplasm of tumor cells, and only a few tumor cells showed positive ZC3H15 staining in the nuclei." (PMID 27191988, 2016). "We determined the ZC3H15 levels by quantitative RT-PCR and immunohistochemistry (IHC) in a retrospective cohort of tumor tissues and matched normal tissues samples from HCC patients after liver resection." (PMID 27191988, 2016). "This discovery suggests that the regulation of the AKT-mTOR signaling pathway by ZC3H15 may have broader implications in tumor biology." (PMID 41513632, 2026). "In addition, clinical case-related factor analysis showed that high ZC3H15 expression levels correlated with tumor size [P = 0.006], TNM stage [P = 0.012] and lymph node metastasis [P = 0.003]." (PMID 41513632, 2026). "It suggested that ZC3H15 participated in the adhesion and metastasis of tumor cells." (PMID 35027542, 2022). "The older the patients, the higher the expression of ZC3H15 in the tumor." (PMID 35027542, 2022). "ZC3H15 mRNA levels were examined in 60 pairs of tumor and normal liver tissues." (PMID 27191988, 2016). "Thus, exploring the cross-talk between ZC3H15 and other signaling pathways, such as the Kras and TGFβ pathways, in future studies will help to fully understand its complex mechanisms in tumor development." (PMID 41513632, 2026). "ZC3H15 expression levels were found to be significantly higher in NSCLC tissue than normal tissue and correlated with tumor size, TNM stage, lymph node metastasis and poor prognosis of patients." (PMID 41513632, 2026). "In this study, we found that ZC3H15 is highly expressed in NSCLC tissues, and that ZC3H15 expression levels are correlated with various clinicopathological parameters of NSCLC, including tumor size, lymph node metastasis, and TNM stage." (PMID 41513632, 2026). "In the present study, we demonstrated that ZC3H15, which interacts with DRG1, is highly expressed in HCC and regulates tumor cell proliferation in vitro and in vivo." (PMID 27191988, 2016). "Using multivariate Cox regression analyses, ZC3H15 expression in HCC tumors correlated with a decreased overall survival rate and increased tumor recurrence." (PMID 27191988, 2016). "Since PTEN negatively regulates the AKT signaling pathway and influences tumor prognosis, we selected PTEN as a candidate protein that might interact with ZC3H15." (PMID 41513632, 2026). "Interestingly, ZC3H15 is able to decrease the mRNA and protein level of CBL through transcriptional regulation, thereby promoting tumor growth." (PMID 35027542, 2022).
tumor (continued). "Assessment of ZC3H15 expression level in the resected HCC tissue may thus provide a valuable indication for effective follow-up management, especially for those patients with modest tumor staging or histopathologic features." (PMID 27191988, 2016).
ZC3H15 also shares sentences with these, for which no sentence is quoted: acute myeloid leukemia (3 papers); coronary artery disease (1); infection (1); inflammatory bowel disease (1); myeloid leukemia (1); non-small cell lung carcinoma (1).